RN7SL446P (RNA, 7SL, cytoplasmic 446, pseudogene)
Gene: Miscellaneous RNA gene on chromosome 4 (152,264,150 to 152,264,445, reverse strand). Ensembl gene ENSG00000244544.
Homologues: Orthologues: chimpanzee Metazoa_SRP (96% identical), macaque Metazoa_SRP (92% identical), rabbit Metazoa_SRP (62% identical). Paralogues in human: RN7SL3 (80% identical), RN7SL1 (80% identical), RN7SL2 (79% identical), RN7SL296P (78% identical), RN7SL230P (77% identical), RN7SL664P (77% identical), RN7SL357P (77% identical), RN7SL448P (77% identical), RN7SL242P (77% identical), RN7SL408P (77% identical), RN7SL481P (77% identical), RN7SL786P (77% identical), and 703 more.